HDAC1 (histone deacetylase 1)
Diseases named in the same sentence as HDAC1 in open-access papers (continued):
Sharing a sentence is not in itself a finding about the gene and the disease.
leukemia (continued). "An association analysis of clinical characteristics revealed that when compared with normal controls, HDAC expression was much higher in human leukemia patients, particularly for HDAC1." (PMID 25341045, 2014). "The discrete number of HP1β foci observed 2 days after HDAC1 induction suggest that these foci colocalize with promyelocytic leukemia bodies as the cells were still in the proliferative phase that preceded senescence." (PMID 17578512, 2007). "Accordingly, there is intense interest to develop isoform‐selective HDACi's, notably of HDAC1 and HDAC6 (and HDAC8) HDAC1 is overexpressed in a wide range of solid tumors as well as in several leukemias and lymphomas, including acute lymphoblastic leukemia (ALL), CLL and AML." (PMID 40370107, 2025). "In addition, either Baicalein or VPA treatment decreased the expression of HDAC‐1 in huCD45+ leukemia cells in bone marrow of primary AML cells (#29)‐bearing mice." (PMID 32898337, 2020). "Also, HDAC1 is found to be involved in leukemia/lymphoma-related factor (LRF)-mediated suppressive effect on the chondrogenic differentiation." (PMID 32950972, 2020). "For example, it will be interesting to determine whether and under which conditions HDAC1 activity influences DOT1L activity in human MLL‐r leukemia and whether the crosstalk is involved in the response of CTLC to HDAC inhibitors in the clinic." (PMID 31304633, 2019). "Interestingly, we observed that Hdac1Δ/Δ; Hdac2Δ/Δ Eμ-myc mice had significantly lower PBL counts, compared to control Hdac1+/+; Hdac2+/+ Eμ-myc mice, and hence reduced leukemia burdens." (PMID 27886239, 2016). "HDAC1 expression levels in the cells of leukemia patients were significantly higher than controls." (PMID 25341045, 2014). "The in vivo tumorigenesis results provide more evidences that the inhibition of HDAC1, overexpression of Klf4, or a combination of the two may provide a novel way to treat leukemia in humans." (PMID 25341045, 2014). "Knockdown of HDAC2 induces apoptosis of leukemia cells, which is different from HDAC1 knockdown." (PMID 25341045, 2014). "In our study, modulation of Klf4 expression can mimic the effects of HDAC1 in leukemia cells." (PMID 25341045, 2014). "Thus, HDAC play an important role in APL, however their role varies over time as HDAC1/2 knockdown in early leukemogenesis expands the leukemia, whereas in leukemic phase, knockdown of the same HDAC1/2 cause differentiation and apoptosis of APL cells, and increased survival of APL mice." (PMID 30304859, 2018). "Moreover, overexpression or knockdown of Klf4 could markedly block the effects of HDAC1 overexpression or knockdown on leukemia cells in vitro and in vivo, respectively." (PMID 25341045, 2014). "Comparing the mechanisms by which belinostat and its hydrazide analogs exert anti-cancer effects allows for an assessment of the individual roles of HDAC1 and HDAC3 in the survival of specific leukemia and lymphoma cell types." (PMID 40284412, 2025). "Instead, consistent with previous findings on the physical interaction between HDAC1 and NICD in leukemia cells, we validated NICD-HDAC1 interactions in SJSA-1 and 293T cells." (PMID 38043798, 2024). "Chidamide is an oral selective histone deacetylase (HDAC) inhibitor that selectively inhibits HDAC1, HDAC2, HDAC3, and HDAC10, inducing apoptosis and growth arrest in leukemia cells." (PMID 39040100, 2024). "Even primary leukemia AML cells (#2, #28) with low background expression of HDAC‐1, Baicalein inhibited the expression of HDAC‐1 protein as well." (PMID 32898337, 2020). "MS‐275, which preferentially targets HDAC1 and HDAC3, is reported to induce acute ROS in human leukemia cells." (PMID 31668005, 2019). "Knockdown of HDAC1 can mimic the effects of VPA and mocetinostat by inducing cell cycle arrest and inhibiting leukemia cell proliferation." (PMID 25341045, 2014).
leukemia (continued). "To investigate the significance of Class I HDACs (HDAC1, HDAC2, HDAC3, and HDAC8), HDAC11, and Klfs (Klf1, KLf3, Klf4, and Klf7) in the pathogenesis of human leukemia, we used real-time RT-PCR to evaluate the expression of HDACs and Klfs in bone marrow samples from human leukemia patients." (PMID 25341045, 2014). "Our findings imply that treatment with HDAC1 inhibitors may sensitize leukemia cells to PARP inhibitors, a class of drugs not previously thought to be effective in treating AML." (PMID 41214140, 2026).
viral infection (25 papers, 2013 to 2026). "Specifically, we infected HDAC1-cKO and WT mice with the clone 13 strain of LCMV (LCMV Cl13), which results in chronic viral infection accompanied by a temporal weight loss and hepatitis driven by CD8+ T cells." (PMID 40464916, 2025). "In the context of viral infection, HDAC1 plays a crucial role in enabling transcriptional activation of ISGs through IRF3 (35, –, 37)." (PMID 39927774, 2025). "Taken together, our results demonstrate a CD8+ T cell–intrinsic key role for HDAC1 not only for the generation but also for the maintenance of the Texeff-like cell population during chronic viral infection." (PMID 40464916, 2025). "HDACs are implicated in viral infections; for instance, Marek’s disease virus (MDV) interacts with HDAC1 and HDAC2 to facilitate their degradation, while the knockout of HDAC9 enhances foot-and-mouth disease virus (FMDV) replication." (PMID 40938964, 2025). "While another reported showed that Influenza A virus dysregulates host histone deacetylase 1 that inhibits viral infection in lung epithelial cells." (PMID 39035358, 2024). "The qRT-PCR results were consistent with Western blot results showing that 3D protein expression increased but HDAC1 was suppressed after viral infection." (PMID 37162335, 2023). "All designed compounds exhibited effects against BRD4 and HDAC class I, mainly HDAC-1 and -2, being promising prototypes to be evaluated against viral infections by acting through epigenetic mechanisms." (PMID 34959707, 2021). "Since the virus infection led to protein depletion of HDAC1, 2, 3 and 4, we then examined the roles of histone acetylation in BoHV-1 infection by using two chemical inhibitor TSA and Anacardic acids (AA)." (PMID 34445287, 2021). "Of interest, our own past work has revealed that TRIM28/KAP1 selectively binds IN post-translationally modified by acetylation and that, in complex with HDAC1, curtails viral infection by promoting IN deacetylation." (PMID 30804369, 2019). "All members of this family share a conserved seed region that can potentially bind to the 3’ UTR of HDAC1 and all of these miRNAs have the potential to cooperate to negatively regulate HDAC1, and other targets, during virus infections." (PMID 24086750, 2013). "The highly induced miR-449b was found to target the HDAC1 mRNA, leading to mRNA and protein interference, and subsequent regulation of IFNβ gene expression during stimulation with double stranded RNA and virus infection." (PMID 24086750, 2013). "Since previous studies have shown that the Texeff-like cell pool is maintained throughout chronic viral infection, we next examined whether HDAC1 is also essential for the maintenance of Texeff-like cells." (PMID 40464916, 2025). "The AKT-mTOR signaling pathway downstream of HDAC1 is critical during viral infection and may regulate the replication of a variety of RNA viruses." (PMID 37162335, 2023). "HDAC1, as the most widely studied deacetylase, plays a significant role in epigenetic regulation of cellular genes and serves as an important regulator of innate immunity during viral infection." (PMID 36070294, 2022). "Moreover, we found that deletion of HDAC1 by viral infection of neural stem cells is sufficient to compromise neuronal differentiation in vitro." (PMID 35095417, 2021). "Next we determined whether HDAC1/HDAC2 also control CD4+ CTL generation in response to viral infection in vivo." (PMID 32102981, 2020). "We speculated that downregulation of HDAC1 at the early stage in IAV-infected cells might be a self-host protective response to the virus infection, which may be critical to activate the IFN-α expression." (PMID 29312300, 2017). "Moreover, we studied whether CD8+ T cell function and effector differentiation are regulated by HDAC1 under steady state conditions and during viral infection using Cd4Cre-mediated deletion of HDAC1." (PMID 25333902, 2014).
viral infection (continued). "Specifically, it has been demonstrated that HDAC1 is required for IFNβ gene repression and siRNA-mediated depletion of HDAC1 results in de-repression of IFNβ gene transcription, producing a higher level of IFNβ in response to virus infection or dsRNA treatment." (PMID 24086750, 2013). "Conversely, the activation of histone deacetylase 1 has been found to enhance PEDV replication in porcine IPEC-J2 cells, highlighting the significant role of histone acetylation in viral infections." (PMID 40336815, 2025). "Specially, TET3 can function in a DNA demethylation-independent manner and binds to the IFN-β promoter and leads to the recruitment of HDAC1 to the IFN-β promoter, consequently inhibiting IFN-β transcription under viral infection." (PMID 36070294, 2022). "So, HDAC1 and HDAC3 can stimulate host antiviral response or inflammatory response, which tend to be depressed by virus infection." (PMID 30261679, 2018). "The colocalization of IE1 with HDAC1 and HDAC2 was also observed in HF cells during the early stage of virus infection." (PMID 25812002, 2015). "Previous work suggested that inhibition of HDAC1 could trigger a cellular DNA damage response that resulted in the activation of cGAS; however, our data suggest that, at least in THP1 cells, viral infection is required for VPA to induce an IFN-I response." (PMID 38932169, 2024). "Nevertheless, we detected no change in proliferation after HDAC1 was knocked out in HPSCs HDAC1 by viral infection." (PMID 35095417, 2021). "The unexpected decreased expression levels of both HDAC1 and HDAC3 may undermine the finding that virus infection decreased the acetylation of histone H3." (PMID 30261679, 2018). "Furthermore, like HDAC1, HDAC2 also has been shown to undergo ubiquitination and consequently proteasomal degradation during virus infection as well as heterologous conditions." (PMID 28769891, 2017). "However, it seems that downregulation of both HDAC1 and HDAC3 by virus infection was not correlated with the decreased levels of histone H3 acetylation, which emphasized the complexity of the mechanisms for the regulation of histone acetylation following virus infection." (PMID 30261679, 2018).
acute myeloid leukemia (23 papers, 2013 to 2025). Acute myeloid leukemia (AML) is a group of neoplasms arising from precursor cells committed to the myeloid cell-line differentiation. "Pharmacological peptides that specifically disrupt the interaction between SALL4 and HDAC1 have been tested with success as therapeutic agents both in acute myeloid leukemia and hepatocarcinoma." (PMID 38062245, 2024). "Baicalein inhibited the activities of HDAC-1 and HDAC-8 and induced proteasomal degradation of HDAC-1, thereby suppressing tumor cell growth and differentiation in in vitro and in vivo models of acute myeloid leukemia." (PMID 37111207, 2023). "It is previously reported that in acute myeloid leukemia, HDAC1 is displaced from P50 homodimers bound to anti-apoptotic genes, contributing to NF-κB inactivation and c-FLIP downregulation." (PMID 25477070, 2014). "Moreover, HDAC1 is an adverse prognostic factor in patients with acute myeloid leukemia (n = 150, p = 0.02), being a possible complication of MPNs." (PMID 40877230, 2025). "Knocking down Hdac1/Hdac2 also promotes acute myeloid leukaemia and genomic instability." (PMID 29472538, 2018). "Thus, hispidulin may serve as a promising lead compound for HDAC1 modulation, potentially enhancing therapeutic efficacy in the treatment of acute myeloid leukemia (AML)." (PMID 40696057, 2025). "Interestingly, chidamide, which targets HDAC1, 2, 3, and 10, also belongs to the benzamide class but exerts obvious anti-tumor immunity effect in relapsed and refractory peripheral T cell lymphoma and acute myeloid leukemia." (PMID 34504867, 2020). "For instance, in acute myeloid leukemia (AML), the transcriptional complex NF-κB/Sp1 can interact with HDAC1 and HDAC3 to form the NF-κB/Sp1/HDAC complex on miR-29b enhancer, which resulted in the silencing of miR-29b." (PMID 24261995, 2013). "Similarly, in acute myeloid leukemia (AML), exosomal circ_0006896 interacts with HDAC1 to limit antitumor immunity, providing evidence that circRNA-containing EVs can also reprogram myeloid cell differentiation and epigenetic states." (PMID 41438756, 2025). "In Non-Hodgkin B-cell lymphoma and acute myeloid leukemia, c-Myc was also reported to regulate the gene transcription by recruiting HDAC3, while HDAC1/2 were most likely to be recruited to the promoter of MYC and regulated the transcription of MYC." (PMID 35158730, 2022). "In acute myeloid leukemia (AML) MV-4-11 cells, microarray analysis identified respective and overlapping genes altered by an HDAC1/2 inhibitor ACY1035 and a DNA methyltransferase inhibitor azacitidine." (PMID 30939743, 2019). "It has been recently shown that the gene repressors, HDAC1 and HDAC2, became recruited to the promoter of miR-182 and represses it in acute myeloid leukemia." (PMID 29383111, 2017). "In acute myeloid leukemia (AML) cells, YY1 was revealed to bind and interact with HDAC1/3." (PMID 38539569, 2024). "HDAC1 and HDAC2 have been proven to cooperate in regulating BRCA1 transcript and protein expression in acute myeloid leukemia (AML) cells." (PMID 29239146, 2018). "In the referred model of retinoic acid-induced differentiation of acute myeloid leukemia cells LSD1 played a scaffolding role, and LSD1 inhibition impeded the interaction between LSD1 and GFI1, but not with HDAC1/2 and RCOR1." (PMID 34572113, 2021).
lymphoma (22 papers, 2013 to 2025). A malignant (clonal) proliferation of B- lymphocytes or T- lymphocytes which involves the lymph nodes, bone marrow and/or extranodal sites. "Across all HDAC genes which are expressed at higher than medium levels in ALL and lymphoma, HDAC1 has the most impact on cell proliferation." (PMID 40284412, 2025). "Using a spectrum of human lymphoma specimens, we observed high levels of HDAC1 and HDAC2 protein expression in the vast majority of ALCL, angioimmunoblastic T cell lymphoma (AITL), and PTCL cases." (PMID 40175628, 2025). "In both in vitro and in vivo settings, genetic co‐depletion of Hdac1 and Hdac2 was pro‐apoptotic in Eμ‐Myc lymphoma, and this behavior was mimicked by the HDAC1/2‐specific agent RGFP233." (PMID 39428967, 2024). "Thymic lymphomas that arise upon genetic deletion of Hdac1 retained the increased H3K79 methylation and were sensitive to reduced DOT1L dosage." (PMID 31304633, 2019). "In a study evaluating the expression of HDAC1, HDAC2, HDAC6, and acetylated histone 4 (H4) in patients with lymphoma, HDAC1 was found to be overexpressed to a larger degree in patients with PTCL compared with patients with diffuse large B-cell lymphoma." (PMID 28090369, 2016). "Our study showed that VPA and SAHA induced lymphoma cell apoptosis through inactivating HDAC1/P50/c-FLIP axis, indicative an alternative mechanism of HDACIs on NF-κB activation and tumor cell apoptosis in PTCLs." (PMID 25477070, 2014). "Our findings highlighted that c-FLIP was involved in defective apoptosis, tumor progression in PTCLs and related to T-lymphoma cell apoptosis induced by HDACIs through inhibiting HDAC1/P50/c-FLIP axis." (PMID 25477070, 2014). "In this study, our expression profiling of HDAC1–6 in three lymphoma cell lines found the highest expression level of all six isoforms in DoHH2 cells, which were more sensitive to TSA." (PMID 23758695, 2013). "Functioned as an anti-apoptotic protein of extrinsic pathway, c-FLIP reflected tumor progression and resistance to chemotherapeutic agents, but could be targeted by HDAC1-mediated NF-κB inactivation and conferred T-lymphoma cell sensitivity to HDACIs." (PMID 25477070, 2014). "However, ALL and lymphoma cells showed more pronounced sensitivity to HDAC1 depletion." (PMID 40284412, 2025). "For instance, RIP-Seq analysis in lymphoma cells indicated that nuclear eIF4E binds over 3000 mRNAs that encode proteins acting in lymphoma-sustaining pathways such as B-cell receptor signaling (Bcl2, Bcl6) and DNA methylation/epigenetic regulation (DNMT1, DNMT3A, HDAC1)." (PMID 30455716, 2018). "Intriguingly, some reports indicate a tumor-suppressive effect of HDAC1 and HDAC2, especially in T cells, where dosage-dependent deletion of the two HDAC enzymes resulted in induction of lymphomas." (PMID 35954222, 2022). "We found that overexpression of HDAC1 and MDM2 correlated with the presence of lymphomatous effusions, and HDAC1 overexpression also was associated with a poorer prognosis (p = 0.005)." (PMID 34635181, 2021). "We showed that STAT3 interacts with DNMT1 and HDAC1 both in CD8+ T cells and KAI3 NK cells, which is in line with previous studies showing STAT3-DNMT1-HDAC1 complex in lymphoma cells." (PMID 34075200, 2021). "To examine the effect of HDACi treatment or HDAC1 depletion on non-histone protein acetylation in the lymphoma cell lines, we enriched acetylated peptides from the non-chromatin fraction using the PTMScan® Acetyl-Lysine Motif [Ac-K] Kit." (PMID 35954222, 2022). "In MYC-induced lymphoma, HDAC6 has a different function than HDAC1." (PMID 35008680, 2021). "Besides, only the combinatorial knock-down of HDAC1 and HDAC2 led to a huge increase in apoptosis of MYC-driven lymphoma cells." (PMID 35008680, 2021). "An independent cohort of 51 DLBCL cases with (n = 31) and without (n = 20) lymphomatous effusions were immunohistochemically studied to validate the role of MUM4, HDAC1 and MDM2 overexpression in the formation of lymphomatous effusions." (PMID 34635181, 2021).
lymphoma (continued). "Interestingly, we found that human HDAC1, but not human HDAC2, mRNA expression is increased in some Burkitt’s lymphoma (BL) and diffuse large B cell lymphoma (DLBCL) cancer cell lines and human lymphoma samples, when compared to other cancer cell lines or other human cancer samples, respectively." (PMID 27886239, 2016).